EZH2 (enhancer of zeste 2 polycomb repressive complex 2 subunit)
Diseases named in the same sentence as EZH2 in open-access papers (continued):
Sharing a sentence is not in itself a finding about the gene and the disease.
lung cancer (continued). "Similarly, the expression of lncRNA HOTAIR is significantly increased in lung cancer, and it can promote the transcriptional activity of β‐catenin by binding to various proteins related to the Wnt signaling pathway, such as EZH2, enhancing the oncogenic effects of the Wnt pathway." (PMID 39991629, 2025). "In addition, in lung cancer cells, inhibition of either EZH2 or HIF-1α could enhance the other’s function, which suggests that the prognosis for tumors might be enhanced by simultaneously inhibiting EZH2 and HIF-1α." (PMID 38911968, 2024). "Therefore, our hypothesis posits EZH2 as a potential target of NOP2 in lung cancer cells, with NOP2 promoting lung cancer progression through the regulation of EZH2 expression." (PMID 39013911, 2024). "Similarly, in our 7 paired lung cancer brain metastasis tissues, lung cancer tissues, and lung cancer adjacent tissues, EZH2 expression was found to be in the vicinity of the cancer, and the expression in the primary and post metastasis tissues showed a gradually increasing trend." (PMID 38764053, 2024). "In this study, patients receiving chemotherapy underwent a GC genotype mutation at the G553C locus of the EZH2 gene in the primary lung cancer lesion after progression, while patients who did not receive treatment only showed a C genotype in brain metastasis resection samples one month later." (PMID 38764053, 2024). "As RNAPII- and EZH2-mediated interactions showed significant regulation of gene expression, we analyzed whether abnormal expression of oncogenes or tumor suppressor genes is related to abnormal interaction patterns in lung cancer." (PMID 36702236, 2023). "High expression of EZH2 is observed in lung cancer and relates to poor prognosis of lung cancer patients; both knockdown of EZH2 and application of EZH2 suppressors are capable of suppressing cell viability and cell line migrations of lung cancer and enhancing apoptosis and chemotherapy sensitivity." (PMID 38048186, 2023). "Notably, miR-21 has been shown to increase EZH2 expression in human lung cancer stem cells." (PMID 36829176, 2023). "Interestingly, previous studies have reported these genes to play important roles in cancer progression: up-regulation of EZH2 was related to poor prognosis for lung cancer patients, accompanied by potential damage of viability and migration in lung cancer cells." (PMID 37689745, 2023). "Here, the administration of GSK126, alone or in combination with SAHA, did not reduce the proliferation or viability of the SMARCA4def lung cancer cells, implying that EZH2 activity does not, by itself, cause the refractoriness to cell growth inhibition by SAHA in SMARCA4def lung cancer cells." (PMID 34262032, 2021). "For instance, loss of EZH2 was shown to promote genomic instability, to act as a barrier to KRAS-driven inflammation and EMT or to promote therapy resistance in BC, colorectal cancer, lung cancer, acute myeloid and T-cell acute lymphoblastic leukemia, respectively." (PMID 34845197, 2021). "Besides, circ-PRMT5 could effectively sponge miR-498 to alleviate its repression on the well-known oncogenic EZH2, thereby facilitating lung cancer progression." (PMID 32541093, 2020). "In addition, we have investigated the correlation between EZH2 expression and EGFR expression, KRAS expression, BRAF expression, and smoking in TCGA database to further explore the mechanism behind the influence of high EZH2 expression on lung cancer prognosis." (PMID 33299862, 2020). "A study showed that EZH2 downregulation in lung cancers could be used as a treatment." (PMID 31711520, 2019). "The impaired expression of these markers might generate the abnormal cell proliferation in the area of metaplastic epithelium, suggesting a potential involvement of EZH2/H3K27me3/DAB2IP pathway in the progression of inflammatory diseases of the airways toward lung cancer." (PMID 31666665, 2019).
lung cancer (continued). "Thus, we could have the conclusion that FOXF1-AS1 interacted with EZH2 to modulate the metastasis of lung cancer cells." (PMID 27577075, 2016). "Indeed, identification of an immunogenic epitope of EZH2 recognized by CD4 T-cell in lung cancer, could serve as a potent immunogenic target inducing both CD4 and CD8 T-cell anti-tumor responses." (PMID 27793053, 2016). "N-terminal glycine myristoylation confers hydrophobicity to EZH2, which drives LLPS of EZH2 in lung cancer cells, compartmentalizes the substrate STAT3, and activates STAT3 signaling, ultimately facilitating rapid lung cancer cell proliferation." (PMID 40642070, 2025). "EZH2 and MDM2 are critical in lung cancer; the activation of EZH2 accelerates cell growth, promoting rapid tumor progression and facilitating cancer cell dissemination to other organs by inducing EMT, thereby increasing cell mobility and invasiveness." (PMID 40070571, 2025). "Inhibitors targeting EZH2, such as EPZ-6438, and GSK126, can reduce H3K27me3 levels, reactivate tumor suppressor genes, and inhibit the growth and metastasis of lung cancer cells." (PMID 41394878, 2025). "For example, the XIST–EZH2 axis involves XIST recruiting EZH2 to mediate H3K27me3-dependent silencing of CDH1 and KLF2, which promotes the proliferation and migration of lung cancer cells." (PMID 41394878, 2025). "Based on this, we conducted Co-IP assays using A549 lung cancer cells, which revealed that SMARCB1 interacts with MEOX2, GLI-1, and BRD9, with a potential weak interaction with CBP and EZH2." (PMID 39971779, 2025). "Importantly, Liu and colleagues identified that EZH2 could play a tumorigenic role in lung cancer." (PMID 39013911, 2024). "Overall, NOP2 altered the expression of EZH2’s downstream target E-cadherin by regulating EZH2 expression and H3K27me3 mediated by EZH2, and thus promoted EMT in lung cancer cells." (PMID 39013911, 2024). "This new role of PRC2 in cancer has been recently proposed to stem from the ability of its catalytic subunit EZH2 to bind and modulate the transcription of mesenchymal genes during epithelial-mesenchymal transition (EMT) in lung cancer cells." (PMID 39174513, 2024). "Silencing of EZH2 sensitized the lung cancer cells to gefitinib and induced expression of p16 and p21, suggesting that HOTAIR contributes to gefitinib resistance by regulating EZH2/p16/p21 axis." (PMID 38887279, 2024). "Activation of EZH2 increases the proliferation rate of lung cancer cells, and promotes metastasis and EMT resulting in lung cancer progression." (PMID 38836056, 2024). "For instance, TFAP2A potentiates lung adenocarcinoma metastasis and stimulates angiogenesis in lung cancer cells with acquired resistance to anlotinib; TFAP2A-mediated activation of E2F and EZH2 drives melanoma metastasis." (PMID 38890750, 2024). "A novel EZH2 antagonist EIP103 was demonstrated to enter the nucleus, leading to pronounced cytotoxicity and significant anti-tumor activity in lung cancer." (PMID 39513112, 2024). "Myristoylation of EZH2 also augments its interaction with STAT3, thereby enhancing STAT3 Y705 phosphorylation and transcriptional activity, which ultimately propels lung cancer progression." (PMID 38034101, 2023). "In summary, EZH2 expression decouples from PRC2 activity, and a pattern of high EZH2, low H3K27me3 and high FOXP2 is enriched in poorly differentiated advanced lung cancers." (PMID 36670102, 2023).
lung cancer (continued). "Recent studies have demonstrated that interaction and phosphorylation of SOX2 by CDK1 positively regulate stemness in lung cancer, and CDK1 phosphorylation of both HIF-1α and EZH2 promotes tumor cells survival and proliferation." (PMID 37189841, 2023). "Several typical lung cancer-related genes exhibited interactions mediated by CTCF, EZH2, H3K27me3, and especially RNAPII, suggesting a regulatory relationship between the associated chromatin interactions and these genes." (PMID 36702236, 2023). "Fitting with an oncogenic role, high EZH2 expression in the lung is oncogenic, drives sensitivity to pharmacological inhibition of EZH23 and correlates with worse lung cancer prognosis." (PMID 36670102, 2023). "To extend our findings to human lung cancer patient samples, we performed immunohistochemical staining for EZH2, H3K27me3, and FOXP2 on lung cancer tissue microarray." (PMID 36670102, 2023). "In lung cancer, CCL2 expression was attenuated by EZH2-mediated H3K27me3 in the enhancer regions and DNMT1-mediated DNA methylation in the promoter regions, impeding M2-like phenotype of macrophages thereby facilitating metastasis and infiltration." (PMID 37273004, 2023). "Additionally, EZH2 inhibition could reverse gefitinib resistance in lung cancer cells." (PMID 35902569, 2022). "In this way, EZH2 stimulates chemokine ligand 5 (CCL5) to provide macrophage chemotaxis, leading to metastasis of lung cancer cells." (PMID 35236381, 2022). "MiRNA-124 transfection results in down-regulation of EZH2 and subsequent inhibition of EMT, impairing lung cancer migration." (PMID 35236381, 2022). "In hepatoma and nonsmall cell lung cancer (NSCLC), upregulation of circPRMT5 facilitates cancer progression via targeting HK2 or EZH2." (PMID 36161608, 2022). "High expression of EZH2 promotes advanced non‐small cell lung cancer (NSCLC) resistance to cisplatin, and EZH2 has been suggested as a predictive marker for tamoxifen therapy in metastatic breast cancer." (PMID 35253323, 2022). "In the same study, the authors showed that targeting EZH2 with DZNep inhibitor strongly sensitized SCLC cells and tumors (Nu/Nu mice with NCI-H128 lung cancer xenografts) to cisplatin." (PMID 36230683, 2022). "While myristoylation of FUS1 is highly essential for its ability to suppress in vivo tumor growth, myristoylated EZH2 was shown to efficiently bind with STAT3 and promote in vivo lung cancer." (PMID 36226054, 2022). "To investigate the pre-clinical relevance of active FAK and EZH2-mediated signaling in vivo, we performed IHC analysis to detect the protein levels of p-FAK, EZH2, and its corresponding substrate, H3K27me3, in lung-cancer-cells-derived tumor tissue arrays." (PMID 36009484, 2022). "Atractylenolide I inhibits the growth of lung cancer cells by inhibiting PDK1 and LncRNA HOTAIR-mediated EZH2 gene expression." (PMID 34335248, 2021). "It is reported that EZH2 directly interact with LATS2 and E‐cadherin promoter regions and activate H3K27 trimethylation modification in non‐small cell lung cancer 36 and gastric cancer." (PMID 33336896, 2021). "For example, HMGA2 is a binding partner of PCAT6 and contributes to PCAT6-mediated CRC, as well as EZH2 in CRC and lung cancer." (PMID 34327141, 2021). "It has been reported that inhibition of enhancer of zeste homolog 2 (EZH2) contributes to the antitumor effect of HDAC inhibitors in neuroblastoma cells and lung cancer cells." (PMID 33743723, 2021). "LINC01133 exerts oncogenic functions in nasopharyngeal carcinoma and lung cancer by binding to YBX1 and EZH2, respectively." (PMID 34047479, 2021). "Beyond the cell lines, we have identified cytoplasmic EZH2 and complex formation between EZH2 and DLC1 in other lung cancer models, including NSCLC patient-derived xenografts and a mutant KRas mouse lung tumor model." (PMID 34862367, 2021). "LINC00665 can induce resistance to gefitinib via recruiting EZH2 and the activation of PI3K/AKT signaling in lung cancer." (PMID 33407473, 2021).
lung cancer (continued). "Studies have found that smoking can affect the expression of EZH2 through reduced DAB2IP via H3K27me3 in COPD patients and promote the transformation of COPD into lung cancer." (PMID 33299862, 2020). "Through acetylation of EZH2, PCAF enhances the protein stability in order to suppress target gene expression and promote lung cancer cell migration and invasion." (PMID 31908141, 2020). "In gastric and lung cancer Linc00337 seems to decrease the transcription of target genes and bind to DNMT1 or EZH2." (PMID 33054826, 2020). "In“in vitro” experiments we studied the effect of cigarette smoke extract (CSE) on EZH2/H3K27me3/DAB2IP expression, apoptosis, invasiveness, and vimentin expression in 16HBE, primary cells, and lung cancer cell lines (A549) long-term exposed to CSE." (PMID 31666665, 2019). "EZH2 and HDAC were evaluated in two different smoking‐related chemically induced lung cancer cell line tumor progression models." (PMID 31456359, 2019). "We show that the expressions of EZH2 and HDAC increase progressively from benign bronchial epithelial cells to lung cancer." (PMID 31456359, 2019). "The aims of this study were to investigate the link between enhancer of zeste homolog 2 (EZH2) and histone deacetylase (HDAC) in preclinical studies and in human lung cancer tissue microarrays." (PMID 31456359, 2019). "In this scenario we concluded that the habits to cigarette smoke might promote epigenetic modifications of EZH2/H3K27me3/DAB2IP, which the onset of pathogenic mechanisms of COPD, persist even after smoking cessation, encouraging the progression of inflammation toward lung cancer." (PMID 31666665, 2019). "The authors provided several lines of additional evidence for a link between EZH2 and LAT1 in lung cancer." (PMID 30103560, 2018). "For example, TUG1 was overexpressed in small cell lung cancer, and TUG1 down-regulation sensitized lung cancer cells to chemotherapeutic drugs (DDP, Adriamycin and Etoposide) by epigenetically suppressing LIM-kinase 2b (LIMK2b) expression through EZH2." (PMID 30519392, 2018). "The inhibitors targeting EZH2, which is co-overexpressed with SUV39H2 in lung cancer, are being thoroughly researched." (PMID 30348215, 2018). "Recently in lung cancer cells, CUR has been shown to alter the expression of enhancer of zeste homolog 2 (EZH2), by both transcriptional and post-transcriptional mechanisms." (PMID 28611316, 2017). "We reported a global decrease in H3K27 acetylation in a ZEB1-induced EMT lung cancer cell model and suggested that ZEB1 would recruit EZH2." (PMID 28804523, 2017). "Abnormal expression of epigenetic players in lung cancer includes EZH2 overexpression in SCLC and NSCLC, where EZH2 acts as an oncogene in these tissues." (PMID 28672805, 2017). "EZH2, a catalytically active component of the PRC2 complex, is one of the targets currently being evaluated for the treatment of lung cancer." (PMID 29156731, 2017). "Knocking down linc00152 suppressed cell invasion and affects prognosis via interacting with EZH2 and repressing IL24 expression in lung carcinoma." (PMID 29285514, 2017). "Finally, it was recently reported that GSK126 can inhibit cell migration and angiogenesis in models of gastric and lung cancer further supporting that this compound effectively suppresses the EZH2-mediated oncogenic pathways may be a promising agent in targeted therapeutics in cancer." (PMID 27793053, 2016). "In the current study, we found that compared with RNAi knockdown of EZH2, knockdown of NOTCH1 mimicked the effects on lung cancer cell proliferation, cell cycle distribution, and cell migration." (PMID 27049834, 2016). "EZH2 inhibition in EGFR and BRG1 mutant lung cancer leads to accumulation of cancer cells in S phase, anaphase bridging and subsequently to increased sensitivity to Topoisomerase II inhibitors." (PMID 27793053, 2016).
lung cancer (continued). "More importantly, our in vivo data were consistent with the findings from that in vitro, confirming the effect of PPI on lung cancer growth inhibition and regulation of SAPK/JNK, p65, DNMT1 and EZH2 protein expression levels." (PMID 27421653, 2016). "Supporting this idea, we observed preferential overexpression of PcG genes CBX2 and EZH2 in SCLC, which represents a lung cancer subtype with neuroendocrine differentiation." (PMID 25859291, 2015). "EZH2 and SUZ12, the components of PRC2, have been found to overexpress in a lot of human cancers, including lung cancer." (PMID 24155936, 2013). "However, the precise role EZH2 played in lung cancer progression remains unclear." (PMID 23300840, 2012). "We found a negative correlation of EZH2 and MLL1 expression (PCC = −0.56) in colon cancer and positive correlation of EZH2 and KDM1A expression (PCC = 0.65) in lung cancer, suggesting cooperation between H3K27 methylation and H3K4 demethylation." (PMID 21886846, 2011). "CONCLUSION: In this retrospective cohort of lung carcinoma patients, high c-MYC expression, but not EZH2 expression, was independently associated with poor OS after adjustment for clinical factors." (PMID 41928013, 2026). "Additionally, protein-protein interactions between EZH2 and SMARCB1 have been identified in eosinophilic leukemia cells, corroborating our findings in lung cancer." (PMID 39971779, 2025). "The authors proposed an intriguing hypothesis that MEG3’s interaction with JARID2 could regulate EZH2 recruitment, thereby facilitating the establishment of H3K27 trimethylation (H3K27me3) in lung cancer cells." (PMID 40149464, 2025). "Collectively, these results demonstrate that NOP2 promotes lung cancer progression by upregulating EZH2 expression, and this promoting effect can be offset by the absence of EZH2." (PMID 39013911, 2024). "SCLC characterized high EZH2 expression and promoted EMT, compared with non‐small cell lung cancer." (PMID 39400978, 2024). "To verify whether ALYREF is a functional m5C reader in lung cancer cells, we performed RIP assay with ALYREF antibody in H1650 and H1299 cells, and the RT-qPCR results showed that ALYREF could bind to EZH2 mRNA, suggesting that ALYREF might be the m5C reader." (PMID 39013911, 2024). "Mirroring data in urothelial cells, we found that the pro-T cell cytokines CXCL9/10/11 are strongly induced by a combination of IFNγ and EZH2 inhibition in both human and murine tumoroids, and that this gene cluster is a direct PRC2 target in human lung cancer cells." (PMID 38265267, 2024). "Importantly, in lung carcinoma cells, the regulation of EMT by EZH2 is mediated by the ability of EZH2 to directly bind the gene promoter regions and co-ordinately modulate the transcription of many mesenchymal-associated genes through H3K27me3." (PMID 39174513, 2024). "Furthermore, inhibition of EZH2 significantly enhanced SLFN11 expression and improves the chemosensitivity of lung cancer cells, thus preventing the emergence of acquired resistance." (PMID 36629984, 2023). "Poorly differentiated human lung cancers were enriched for an H3K27me3-low state, representing a subtype that may benefit from BET inhibition as a single therapy or combined with additional EZH2 inhibition." (PMID 36670102, 2023). "N‐myristoylation of EZH2 promotes phase separation of EZH2 with its substrate STAT3, leading to the activation of STAT3 signaling and growth of lung cancer cells, making N‐myristoylation of EZH2 a potential target for lung cancer therapy." (PMID 37143582, 2023). "However, YAP/TAZ makes a contribution to promoting the evolution of lung cancer through decreasing the expression of TGFBR2 and YAP/TAZ and enhancer of zeste homolog 2 (EZH2) have a synergistic effect in this process." (PMID 37576865, 2023).